IL1B (interleukin 1 beta)
Diseases named in the same sentence as IL1B in open-access papers (continued):
Sharing a sentence is not in itself a finding about the gene and the disease.
cancer (continued). "Based on the CANTOS trial evaluating the effect of canakinumab on preventing adverse cardiac events, Novartis is leading several clinical trials targeting IL-1β in cancer, including three in phase III in NSLC." (PMID 35517498, 2022). "IL-1β can also induce MDSCs, which is one of the major suppressors of antitumor immunity and a crucial element in cancer progression and metastasis." (PMID 36237303, 2022). "IL-1β–induced suppression of antitumor immune responses through the recruitment of MDSCs was demonstrated in various cancer models." (PMID 35471938, 2022). "Altogether, these data show that IL1β-driven systemic low-grade inflammation in cancer enhances JAM-A expression on circulating monocytes." (PMID 36531986, 2022). "NF-κB pathway was similarly evoked in the liver, WAT, and skeletal muscle, triggering inflammation cascade in cancer cachexia via IL-1β, IL-6, and IL-8, etc.." (PMID 36581870, 2022). "In cancer, IL-1β has pleiotropic effects on immune cells, cancer cell proliferation, and metastasis." (PMID 36430236, 2022). "TAT-FADD inhibits the initiation of classic NLRP3 inflammasomes and limits the processing and secretion of pro-inflammatory IL-1β, thereby regulating the anti-apoptotic and pro-inflammatory NF-κB signal activation in cancer cells." (PMID 35664309, 2022). "The importance of IL-1β in cancer invasion was shown in a squamous cell carcinoma model through the capacity of inducing TNF-α expression." (PMID 35681719, 2022). "Subsequently, IL1-β secreted by TAMs stabilizes intracellular β-catenin potentiating Wnt signaling in cancer cells via NFkB/PDK1 and glycogen synthase kinase 3-beta (GSK3β) inhibition, whereas IL-6 further amplifies inflammation within the TME." (PMID 36613445, 2022). "The results demonstrated a decrease in survival rate and metastasization of cancer cells in the presence of CCL21/IL1β, and IC50 of CCL21 on MCF7 cells was less than that of non-recombinant protein." (PMID 36037155, 2022). "We found that LNCaP cells from enzalutamide-treated animals robustly upregulated IL1β transcript expression compared with cancer cells collected from mice on a control diet." (PMID 36561929, 2022). "Taken together, these data suggested that KRAS/CCL2/IL1B transcripts are overexpressed in human KRAS-mutant cancers and detrimentally affect survival." (PMID 35327394, 2022). "In contrast, targeting IL-1β with canakinumab has raised enthusiasm and holds great promise in cancer therapy." (PMID 35327394, 2022). "Strikingly, anti-IL-1β treatment counteracted PMN-MDSC-mediated immunosuppression and potently prolonged the survival of female mice, further providing the rationale for clinical testing of IL-1β inhibitors in cancer patients." (PMID 36163047, 2022). "By contrast, HLA-I+EMTlo cancer cells were associated with enhanced IL1A, IL1B, and CXCL5 mRNA expression." (PMID 35503263, 2022). "The central mechanism behind cancer-associated cachexia is inflammation involving the overproduction of inflammatory cytokines, especially IL-6, TNF-α, and IL-1β." (PMID 36505042, 2022). "Interleukin-1β (IL-1β) is one of the most powerful cytokines, influencing all the initiation-to-progression stages of many types of cancers and represents an emerging critical contributor to chemoresistance." (PMID 35530309, 2022). "Although several publications have indicated an association between fatigue and systemic cytokines such as IL-1β, IL-2, IL-6, IP-10, and TNF in cancer patients, the results are conflicting." (PMID 36350483, 2022). "Various cytokines, such as TNF-α, TGF-β, IL-10, and especially IL-1β and IL-6, are well studied and have been shown to be involved in the complex crosstalk between cancer initiation/progression and sleep–wake cycles." (PMID 35246220, 2022). "Derivative 9f regulates the epithelial-to-mesenchymal transition (EMT) suppressing the mesenchymal marker vimentin and cancer cell migration in IL-1β-stimulated A549 cells." (PMID 35056161, 2022).
cancer (continued). "We also discovered that AR represses the IL1β gene by binding an androgen response element half-site located within the promoter, which explains the IL1β expression in AR-negative (ARNEG) cancer cells." (PMID 36561929, 2022). "In this review, we will discuss inflammaging in the elderly, specifically concentrating on IL-6 and IL-1β in the context of T lymphocytes, and how inflammation is related to mortality and morbidities, specifically cardiovascular disease and cancer." (PMID 35821823, 2022). "In the transcriptional level, cancer related cytokines including IL-1β, IL-6 and TNF-α were all reduced after IVM treatment." (PMID 36132145, 2022). "The cytokines IL-1β and IL-15 are important in the development of inflammatory and protective immune responses to microbes and cancer." (PMID 36119067, 2022). "The connections of TNFα, IL-1β and IFNγ with the PD-L1/PD-1 axis, as well as with cancer-related inflammation, have led us to characterize the impact of these cytokines—each alone and in different combinations—on the expression of PD-L1 by TNBC cells." (PMID 35884574, 2022). "IL-1β blockade also enhanced the apoptosis of cancer cells, characterized by increased expression of cleaved caspase-3 (CC3) and cleaved PARP (c-PARP) measured by Western blot (WB)." (PMID 35471938, 2022). "IL-1β produced by TAMs or released from cancer cells can also boost the pro-tumorigenic activity of CAFs, highlighting its role as a master orchestrator of tumorigenesis." (PMID 35517498, 2022). "It has long been recognized that metastasis can be enhanced by acute or chronic inflammation, such as in response to IL-1β or LPS, which induces endothelial adhesion molecules that facilitate adhesion of cancer cells to ECs." (PMID 35918322, 2022). "In RT-qPCR analysis, the relative mRNA expression level of IL1B in the gastric mucosa was significantly higher in the cancer group than that in the control group (Mann–Whitney test, p = 0.030)." (PMID 36501012, 2022). "Paclitaxel, a microtubule poison, induces apoptosis of cancer cells and activates IL-1β, IL-8, IL-6, thus, enhancing pro-tumorigenic inflammation." (PMID 36611932, 2022). "The data set a rational framework for the future development of effective KRAS inhibitors and design of clinical trials aimed at targeting IL-1β in cancer." (PMID 35327394, 2022). "Both IL-1β and IL-18 lead to the infiltration of more immune cells and result in the generation and maintenance of an inflammatory microenvironment surrounding cancer cells, however, the biofunctions are diverse." (PMID 35739593, 2022). "Two major, closely related IL-1 family members, IL-1α and IL-1β, promote tumorigenic phenotypes and contribute to treatment resistance in cancer." (PMID 35626710, 2022). "Increased IL-1β levels in body fluids are correlated with worse cancer prognosis, chemoresistance and invasiveness." (PMID 35986089, 2022). "The expression of selected 6 PRGs (GSDMC, GSDMD, GSDME, NLRP3, NLRC4, and IL1B) was assessed in 6 types of cancers and adjacent normal tissues." (PMID 36605187, 2022). "In tumors, IL-1B is produced and secreted by a variety of cell types, like immune cells, fibroblasts, or carcinoma cells." (PMID 35153782, 2022). "It was reported that high concentrations of serum IL-1β and IL-18 are strictly correlated to poor prognosis of cancer patients." (PMID 34211462, 2021). "The knockdown of P2X7 receptors with the utilization of selective or specific antagonists (A-438079, A-740003, and A-839977) benefits cancer pain by reducing the release of cytokine, such as Il-1β." (PMID 34268121, 2021). "Recently, selective inhibitors of IL-1β, IL-6 and IL-8 are proposed in cancer patients aimed to improve anticancer effects of selective inhibitors of kinases and immune check-point inhibitors, reducing their toxicity." (PMID 34178667, 2021). "Together with our results, it is evident that the IL-1β initiates vascular events, which can advance cancer cells to undergo VM." (PMID 34055597, 2021).
cancer (continued). "More recently, researchers have begun to study the therapeutic potential of TNFα and IL-1β inhibition in cancer." (PMID 33776573, 2021). "Inflammatory pathways are linked to carcinogenesis and progression, and cancer patients often have elevated levels of pro-inflammatory cytokines (TNF-α, IL-6, and IL-1β) and expansion of regulatory cells (myeloid-derived suppressor cells and Tregs)." (PMID 34239993, 2021). "P2RX7 signaling activates the NLRP3 inflammasome, which in turn induces the secretion of active IL-1β, this cytokine playing an important role in the amplification of an efficacious anti-cancer immunity." (PMID 33806300, 2021). "Antibody neutralization of IL-1β and use of IL-1R antagonists showed significant anti-cancer effects in preclinical studies, and their safety was confirmed." (PMID 33686176, 2021). "Development of inhibitors to suppress overactivated IL-1β signalling activity represents one of the cancer therapeutic strategies for inflammasome inhibition." (PMID 33918087, 2021). "By coculturing adipocytes with cancer cells, a surge in the levels of different proteases and cytokines (such as IL-6 and IL-1β) and a reduction in adipocyte-related markers are observed." (PMID 34202411, 2021). "Cancer can produce many factors such as IL-1β, CCL2, TGF-β, G-CSF and GM-CSF influencing innate immune cells, including neutrophils." (PMID 34674757, 2021). "The present study analyses the expression of selected genes and miRNAs associated with inflammatory processes to better understand their contribution to cancer-related inflammation:IL-1β—secreted by macrophages." (PMID 33658555, 2021). "At the molecular level, inflammation leads to the production of inflammatory cytokines, such as IL-6, IL-1β, and TNF, which have been associated with cardiovascular disease and several different types of cancer." (PMID 34234868, 2021). "In vivo studies assessing CYP activity in cancer patients have assessed concentrations of the pro-inflammatory mediators IL-1β, IL-6, IL-8, TNF-α, TGF, and the acute phase response protein, CRP15,20,25." (PMID 33707475, 2021). "For example, ZEB1 controls inflammatory factor IL6, IL8 and IL1β production, which can induce cancer metastasis." (PMID 34916487, 2021). "On the other hand, knockdown of NLRP3 expression inhibited the growth of cancer cells and reduced caspase-1 activation and IL1β maturation." (PMID 34064909, 2021). "Accordingly, the potential of solely blocking IL-1β in cancer treatment needs to be carefully evaluated in the clinical setting as well." (PMID 33530653, 2021). "The nex-IL1β-mRNA in the NK cell nucleus upregulates antiapoptotic gene expression, migration activity, and interferon-γ production, leading to the killing of cancer cells and antimetastasis in mice." (PMID 34135341, 2021). "Another aspect linking NLRC4 and IL-1β with cancer involves their role in promoting the progression of diet-induced mammary tumors in obese mice." (PMID 34276697, 2021). "Other work has echoed these findings further substantiating the clear influence of IL-1β in cancer cachexia genesis." (PMID 33907915, 2021). "Functional disparities between IL-1α and IL-1β blockade in preclinical cancer models have been observed." (PMID 33530653, 2021). "In patients with pancreatic cancer, Fogelman and co-workers showed that IL-1β levels were predictive of development of cancer cachexia and was superior in this regard to other cytokines." (PMID 33907915, 2021). "IL-1β has also shown to promote proliferation in cancer cells by activating several oncogenic signaling pathways." (PMID 34684819, 2021). "Our results, consistent with the previous studies, indicated that CD276, IL1B, LYVE1 and VEGFC are associated with cancer progression." (PMID 33995379, 2021).
cancer (continued). "As mentioned, the pleiotropic functions of IL-1β in cancer immunity have recently and extensively been reviewed." (PMID 33530653, 2021). "Once activated, NLRP3 inflammasome induces the release of pro-inflammatory cytokines IL-1β and IL-18, which can contribute to cancer progression." (PMID 34681768, 2021). "It follows that as the pathophysiological mechanisms of cancer cachexia are mediated by IL-1β, targeting this is a logical approach." (PMID 33907915, 2021). "In conclusion, IL1β-secreted by cancer cells modify surrounding normal fibroblasts to confer protumorogenic features on them, particularly tolerance to cytotoxic drugs." (PMID 34066976, 2021). "Chemokines and cytokines affect different stages of the metastatic process, and in bone metastases, interleukin (IL) -6, IL-8, IL-1β, and IL-11 participate in the interaction between cancer cells and bone cells." (PMID 34201209, 2021). "Instead of the other six cancer-related genes, IL1β is also listed as a potential target of lung cancer study." (PMID 33995625, 2021). "The other possibility is through H2S mediated persulfidation of NF-κB p65 subunit and subsequent activation of NF-κB/IL-1β signaling since IL-1β is a known pro-angiogenic cytokine during cancer progression through induction of VEGF." (PMID 34207284, 2021). "While in general, most reports focus on the protumoral effects of IL-1β in cancer biology, the authors highlighted antitumoral functions of IL-1β as well, raising important considerations for future developments of IL-1 blocking strategies in cancer." (PMID 33530653, 2021). "IL-6 induces programmed cell death protein 1-dependent immunosuppression in cancer, and IL-1β is one of the most important pro-inflammatory mediators involved in chemo-resistance." (PMID 34178667, 2021). "Methylene Blue, a broad-spectrum inflammasome inhibitor 65, and CASP1 siRNAs were used to suppress inflammasome signaling activation, reflected by decreased IL-1β expression, in cancer cells." (PMID 34815793, 2021). "NLRP3 inflammasome activation, caspase-1 activation, release of IL-1β and IL-18 pro-inflammatory cytokines and gasdermin D-mediated pyroptotic cell death are important mechanisms involved in inflammation-induced cancer." (PMID 34452150, 2021). "Work to date highlights the key role of IL-1β in the central mechanisms of cancer cachexia supported by emerging clinical trials." (PMID 33907915, 2021). "In this review, we will discuss cell type- and microenvironmental condition-dependent roles of the inflammasomes and their principal effector molecule, IL-1β, in the development and progression of various types of cancers." (PMID 33686176, 2021). "In view of the powerful roles of CAFs in regulating cancer progression, we explored the possibility that CAFs obtained following persistent stimulation of MSCs by TNFα + IL-1β undergo alterations in the expression of cancer-related genes." (PMID 33806906, 2021). "IL-1α, IL-1β, and IL-18 have been investigated in many types of cancer with both pro- and anti-tumorigenic functions mediated by different cells." (PMID 33840390, 2021). "The expression profile of inflammation- and cancer-related genes (IL-1β, IL-8, TNF-α, IFN-γ, IL-6, NF-κB, and IL-13) were measured using qPCR." (PMID 37901256, 2021). "Cancer patients receiving oral fucoidan for 4 weeks showed reduced levels of proinflammatory cytokines, including IL-1β, IL-6 and TNF-α." (PMID 34436263, 2021). "Expressed by innate immune cells, IL-1β has been demonstrated to play a role in many inflammatory diseases, as well as in different cancers." (PMID 34163438, 2021). "Adhesion assay showed that more SKOV3 or A2780 cells were adhered to MeT-5A cell monolayer pretreated with cancer cell-secreted EVs or TGF-β1 plus IL-1β compared to control cells." (PMID 33726799, 2021). "Basal IL-1β gene expression was lower in both cancer groups when compared to CTL, with a significant difference in WSC and a trend for CC." (PMID 34630405, 2021).
cancer (continued). "For example, monoclonal antibodies targeting IL-1α or IL-1β have shown promise as potential cancer therapies, and the IL-1 receptor antagonist Anakinra has shown efficacy in pre-clinical models of PDA." (PMID 32329713, 2020). "CCAAT/enhancer binding protein β (C/EBPβ) is a transcription factor shown to inhibit myogenesis during cancer cachexia, and it is induced in myoblasts by IL-1β." (PMID 32824440, 2020). "While in macrophages, hypoxia is triggering increased IL-1β expression, on cancer cells, the opposite was observed." (PMID 32231135, 2020). "There is ample evidence demonstrating that in many different types of cancer, including malignancies in skin, colon and lung, upregulated expression of IL-1β correlates with progression of disease." (PMID 33584721, 2020). "C/EBPβ is a transcription factor induced by inflammation (i.e., IL-1β) that blocks myogenic differentiation during cancer cachexia." (PMID 32824440, 2020). "Mutational activation of BRAF contributes to constitutive activation of NF-κB, the key transcriptional factor that controls the production of many cytokines, including IL-1β, and is usually activated by chemotherapy and in cancer drug resistance." (PMID 33396632, 2020). "IL-1β, a recognized product of pyroptotic cell death and key cytokine in cancer progression, has already been selected as a target for cancer immunotherapy." (PMID 31685946, 2020). "Up to date, lots of evidence in both in vitro and in vivo experiments suggest that IL-1β possesses a promoting effect on cancer development and progression." (PMID 33015196, 2020). "Previous studies have shown that phosphorylation and degradation of the IκBα protein promotes the activation of NF-κB and the expression of TNF-α, IL-1β, and IL-6, participating in the formation and development of cancer pain." (PMID 32431607, 2020). "It is therefore likely that macrophages can promote cancer stemness and metastasis also through the secretion of IL-1β." (PMID 33371274, 2020). "IL-1β is elevated in various types of cancers, and IL-1β-producing tumors showed a worse prognosis in the Human Protein Atlas." (PMID 31992771, 2020). "The fact that IL-1β can be produced endogenously and/or by cancer cells highlights the importance of the microenvironment, and more particularly immune cells, in IL-1β-mediated effects." (PMID 32635472, 2020). "Cancer cells gain drug resistance through a complex mechanism, in which nuclear factor-κB (NF-κB) and interleukin-1β (IL-1β) are critical contributors." (PMID 32899791, 2020). "Recombinant IL-1β enhances the sphere-forming capacity of cancer stem cells (CSCs) by increasing stemness gene expression (Bmi1 and Nestin)." (PMID 32635472, 2020). "This pro-angiogenic role was observed even when IL-1β was produced by different cell types, that is, cancer cells or myeloid cells." (PMID 32635472, 2020). "Inflammatory diseases and cancer have been documented to possess an excess of pro‐inflammatory molecules such as IL‐1β, TNF‐α, NO and ROS." (PMID 31680470, 2020). "In cancer, IL-1β has pleiotropic effects on immune cells, angiogenesis, cancer cell proliferation, migration, and metastasis." (PMID 32635472, 2020). "In this context, increased IL-1β provides a nurturing niche for cancer stem cells, promoting angiogenesis and metastasis formation, and taming adaptive immune response." (PMID 32825489, 2020). "All these data suggest that IL-1β is a pivotal contributor to cancer development and has the potential to be validated as a therapeutic target in the constant fight against cancer." (PMID 33015196, 2020). "Another promising target for cancer therapy is IL-1β that promotes recruitment and proliferation of myeloid cells into TME." (PMID 32823961, 2020).